ENSG00000212168
Synonyms: LOC124900539
Gene: Small nucleolar RNA gene on chromosome 2 (57,544,535 to 57,544,599, forward strand). Ensembl gene ENSG00000212168.
Gene Ontology:
Biological process: RNA processing
Cellular component: nucleolus
Homologues: Orthologues: rat LOC120101365 (74% identical).